ANKRD34B (ankyrin repeat domain 34B)
Synonyms: DP58
Tractability: No criterion of Open Targets' tractability assessment is met for any kind of drug.
Gene: Protein-coding gene on chromosome 5 (80,556,755 to 80,570,479, reverse strand). Ensembl gene ENSG00000189127.
Subcellular location: Cytoplasm; Nucleus
Subcellular location (Human Protein Atlas): Mitochondria; Nucleoplasm; Cytosol
Gene Ontology:
Cellular component: cytosol; pi-body; cytoplasm; nucleus
Genetic constraint (gnomAD): Missense variants: 390 observed, 455.05 expected, observed/expected ratio (o/e) 0.86, 90% interval 0.79 to 0.93. Synonymous variants: 154 observed, 173.52 expected, observed/expected ratio (o/e) 0.89, 90% interval 0.78 to 1.01.
Homologues: Orthologues: chimpanzee ANKRD34B (99% identical), macaque ANKRD34B (97% identical), pig ANKRD34B (91% identical), dog ANKRD34B (88% identical), rat Ankrd34b (82% identical), mouse Ankrd34b (81% identical), tropical clawed frog ankrd34b (65% identical), guinea pig ANKRD34B (61% identical), zebrafish ankrd34bb (52% identical), zebrafish ankrd34ba (47% identical). Paralogues in human: ANKRD34A (35% identical).
Diseases named in the same sentence as ANKRD34B in open-access papers:
ANKRD34B is named in the same sentence as 4 diseases in open-access papers, as found by Europe PMC text mining. Sharing a sentence is not in itself a finding about the gene and the disease. The quoted sentences say what the papers report.
amyotrophic lateral sclerosis (1 paper, 2020). Amyotrophic lateral sclerosis (ALS) is a neurodegenerative disease characterized by progressive muscular paralysis reflecting degeneration of motor neurons in the primary motor cortex, corticospinal tracts, brainstem and spinal cord. "In mouse amyotrophic lateral sclerosis, the expression of ANKRD34B is down-regulated and plays roles in axon outgrowth and synapse formation in motor neurons." (PMID 32309439, 2020).
bacterial meningitis (1 paper, 2020). Inflammation of the membranes surrounding the brain and spinal cord due to a bacterial infection. "In the peripheral blood of patients with bacterial meningitis, ANKRD34B is the most remarkably down-regulated gene." (PMID 32309439, 2020).
tumor (2 papers, 2022 to 2023). "An appropriate study design and methylation detection technique are required to demonstrate a possible epigenetic lineage of tumor cells, such as that indicated by a sequence of risk factor-increased methylation of ANKRD34B and/or ZIC1 in normal cells and a further increase in derived tumor cells." (PMID 35628134, 2022). "ANKRD34B and ZIC1 were evaluated as candidate genes by pyrosequencing of 539 tissues, including 239 normal autopsy, 157 histopathologically tumor-adjacent normal, and 143 paired tumor kidney samples." (PMID 35628134, 2022).
cancer (1 paper, 2022). A tumor composed of atypical neoplastic, often pleomorphic cells that invade other tissues. "Common cell line models of prostate, breast, urothelial, renal, and other cancers were used to estimate whether hypermethylation of ANKRD34B and ZIC1 can occur with relevant frequency in human tumors." (PMID 35628134, 2022). "Thus, the newly identified ANKRD34B and ZIC1 cancer loci double the number of age-independent susceptibility loci detected in normal kidney tissue, and strengthen the hypothesis that more as yet unidentified loci may exist." (PMID 35628134, 2022). "Both ANKRD34B and ZIC1 have been reported in a pan-cancer analysis to be targets of PRC2, with hypermethylated CGIs." (PMID 35628134, 2022).